RYR2 (ryanodine receptor 2)
Diseases named in the same sentence as RYR2 in open-access papers (continued):
Sharing a sentence is not in itself a finding about the gene and the disease.
Iron deficiency anemia (4 papers, 2019 to 2023). "A previous mouse model of iron deficiency reported a reduction in RYR2 expression in cardiac lysates." (PMID 35050131, 2021). "In iron deficiency, the concurrent decrease in RyR2 and SERCA activities maintains the pump-leak balance close to control levels, which explains the unaltered diastolic SR Ca2+ loading in iron-deficient mice." (PMID 30779710, 2019). "Remodeling of cardiac Ca2+ signals in iron-deficiency anemia relates to downregulated RyR2 channels and dephosphorylation of the SERCA regulator phospholamban." (PMID 30779710, 2019). "Dual RyR2-SERCA remodeling in iron-deficiency anemia highlights the well-established notion that modulating RyR2 activity alone cannot stably change CaT amplitude." (PMID 30779710, 2019). "Previous studies have observed a decrease in cardiac contraction, both in vivo and in vitro, via downregulation of RyR2 channels and the sarco/endoplasmic reticulum Ca2+-ATPase (SERCA) pump activity in iron-deficiency anemia." (PMID 33553263, 2020). "Consequently, the following points were assigned: overdose (2 points), rivaroxaban (2 points), anemia (1 point), CrCl <30 mL/min (2 points), RYR2 rs12594GG (2 points), rs17682073 AA (1 point), rs6678625 T allele (2 points), and rs3766871GG (3 points)." (PMID 38034995, 2023). "The complexity of iron-deficiency anemia opens myriad possibilities as to how Ryr2 expression changes, but none is direct, as the gene is not HIF regulated nor does it possess an IRE in either its 5′ or 3′ UTR." (PMID 30779710, 2019).
memory impairment (4 papers, 2016 to 2025). "Downregulation of RyR2 channels, however, is likely to produce substantial memory impairments, since RyR2-mediated Ca2+ release is required for rodent hippocampal synaptic plasticity and spatial memory." (PMID 30574085, 2018).
Obesity (4 papers, 2013 to 2018). Accumulation of substantial excess body fat. "This conclusion is supported by the significant increase in CaMKII-mediated phosphorylation of RyR2 in β cells from human type 2 diabetic donors and from our obesity-associated type 2 diabetic (HFD) mouse model." (PMID 23516528, 2013). "Increased RyR2 activity, evidenced by increased sparks frequency, has been reported in the fructose-induced obesity model." (PMID 29439404, 2018). "Increased mRNA expression of the RyR2 has also been shown in a rat model of obesity, and further underscores an important role for RYRs in ventricular arrhythmias associated with metabolic disorders." (PMID 28680407, 2017). "Obesity is characterized by an increased generation of ROS, which may impact RyR2 function and affect the heart rhythm." (PMID 29439404, 2018). "Since obesity promotes oxidative stress and RyR2 are redox-sensitive channels, we investigated whether the RyR2 activity was altered in obese mice." (PMID 29439404, 2018). "There was upregulation of RYR2 mRNA (responsible for the SR Ca2+ release channel) in obesity." (PMID 27747100, 2016). "We have shown that a diet rich in saturated fats leading to obesity results in significant upregulation of Cav1.2, HCN4, Kir2.1, NCX1, SERCA2a, and RYR2 mRNA and significant downregulation of ERG mRNA in the left ventricle." (PMID 27747100, 2016). "Obesity increases the expression of NOX4; this ROS-generating enzyme could be responsible for the redox modification of RyR2 in obese mice." (PMID 29439404, 2018).
pulmonary hypertension (4 papers, 2020 to 2025). Increased pressure within the pulmonary circulation due to lung or heart disorder. "In RHF and models of pulmonary hypertension or pressure overload, RyR2 channels become hyperactive due to oxidative and phosphorylation-mediated remodeling, resulting in increased diastolic Ca2+ release and SR Ca2+ depletion." (PMID 40650137, 2025).
Sepsis (4 papers, 2020 to 2025). Sepsis is defined as life-threatening organ dysfunction caused by a dysregulated host response to infection. "Immunofluorescence and qPCR showed that TLR7 deficiency reduced the expression of Serca and RyR2 in response to sepsis." (PMID 33463061, 2021). "It is known that the atrial activity of the Ca2+/calmodulin-dependent protein kinase II (CaMKII) is higher during sepsis and causes hyperphosphorylation of cardiac ryanodine receptor 2 (RYR2) channels preventing neuronal excitotoxicity, smooth muscle relaxation, vasodilation, and immunomodulation." (PMID 37687017, 2023). "More importantly, our results showing that stabilizing the RyR2 with dantrolene can prevent sepsis‐induced cell death suggests the potential use of this agent for the treatment of the adverse remodelling associated with sepsis." (PMID 33460250, 2020). "Taken together, these results suggest that CaMKII‐dependent RyR2 phosphorylation, possibly through the enhancement of SR Ca2+ leak, is functionally involved in sepsis‐induced cell death." (PMID 33460250, 2020). "We further tested the involvement of RyR2 in sepsis‐induced cell death by using dantrolene, a pharmacological compound known to reduce RyR2 open probability." (PMID 33460250, 2020). "Limitations: Our results using dantrolene suggest that reducing RyR2 open probability can protect the heart from sepsis‐induced apoptosis and improve survival." (PMID 33460250, 2020). "We show that in sepsis, cardiac cell death involves CaMKII activation, which through the phosphorylation of RyR2 enhances SR‐Ca2+ leak leading to mitochondrial Ca2+ overload and apoptosis." (PMID 33460250, 2020). "We conclude that in sepsis, CaMKII‐dependent RyR2 phosphorylation results in diastolic Ca2+ release from SR which leads to mitochondrial Ca2+ overload and apoptosis." (PMID 33460250, 2020). "Indeed, we have recently shown that in sepsis, CaMKII is activated by oxidation and once active it phosphorylates the cardiac ryanodine receptor (RyR2) leading to inappropriate diastolic Ca2+ release from the sarcoplasmic reticulum (SR), known as SR Ca2+ leak." (PMID 33460250, 2020). "Our results using transgenic mice which have a specific point mutation of RyR2 site Serine 2814 mutated to Alanine show that these mice are protected from sepsis‐induced apoptosis providing solid evidence that RyR2 is the RyR isoform involved in sepsis‐induced apoptosis." (PMID 33460250, 2020). "Taken together, these findings propose CaMKII and RyR2 as new therapeutic targets whose inhibition or stabilization, respectively, could serve to ameliorate the cardiac symptoms of sepsis." (PMID 33460250, 2020). "Importantly, we recently showed that, in sepsis, CaMKII‐dependent RyR2 phosphorylation at site Serine 2814 results in enhanced SR Ca2+ leak favouring contractile dysfunction." (PMID 33460250, 2020). "In Porphyromonas gingivalis LPS-induced sepsis in mice, TLR4 caused cardiac dysfunction by activating NADPH oxidase-4, increasing ROS, stimulating calmodulin-dependent protein kinase-II with phosphophorylation of RyR2 and of phospholamban, a negative regulator of SR Ca2+ uptake." (PMID 40649397, 2025). "Thus, we hypothesized that reducing RyR2 open probability with dantrolene could be effective preventing sepsis‐induced cell death." (PMID 33460250, 2020). "Thus, we hypothesized that sepsis‐induced cell death could be, at least in part, due to CaMKII‐dependent post‐translational modification of the RyR2 resulting in SR Ca2+ leak which would be taken up by the mitochondria provoking mitochondrial Ca2+ overload." (PMID 33460250, 2020). "Similarly, in a rat model of sepsis, TLR4 activation by LPS in cardiomyocytes promotes mitochondrial ROS production, oxidation of RyR2 and SR Ca2+ leak." (PMID 40649397, 2025).
Sepsis (continued). "Interestingly, we recently showed that oxidative activation of CaMKII leads to the phosphorylation of RyR2 site Serine 2814, promoting SR Ca2+ leak which in turn reduces SR Ca2+ content and contractility in the CASP model of sepsis." (PMID 33460250, 2020).
sudden infant death syndrome (4 papers, 2015 to 2020). Unexpected death in infancy which remains unexplained following autopsy, review of the medical history, and investigation of the death circumstances and death scene. "A RyR2-S4565R mutation that has been linked to sudden infant death syndrome has been investigated by analyzing Ca2+ release channel activity in vitro." (PMID 30296944, 2018).
astrocytoma (3 papers, 2021 to 2024). "The RYR2 SNP rs16835904 T/C genotype promotes the risk of astrocytoma in men, while SNP rs12594 A/G is associated with overall survival in astrocytoma." (PMID 39408657, 2024). "Mutations in CHECK2, EGFR, PTEN, RYR2, and NF1 are instead associated with an IDH1-wildtype astrocytoma." (PMID 34503108, 2021).
atrial tachycardia (3 papers, 2013 to 2025). A disorder characterized by an electrocardiographic finding of an organized, regular atrial rhythm with atrial rate between 101 and 240 beats per minute. "Recent clinical studies additionally associate RyR2 abnormalities with atrial arrhythmias including atrial tachycardia (AT), fibrillation (AF), and standstill, and sinus node dysfunction (SND)." (PMID 23805105, 2013). "Seven RyR2 mutations are additionally associated with atrial arrhythmic disorders that include atrial tachycardia (AT), fibrillation (AF), and standstill as well as sinus node dysfunction (SND)." (PMID 23805105, 2013). "As RYR2 exon 3 deletion syndrome shows complex CPVT-like phenotypes, including sinus node dysfunction, atrial tachycardia, and atrioventricular node conduction disorder, the patients may present with additional cardiovascular symptoms rather than those of CPVT in the future." (PMID 40606665, 2025).
cognitive decline (3 papers, 2012 to 2025). "Notably, the elevated RyR2 expression, cognitive decline, and synaptic loss observed in patients with MCI, are mirrored by increased RyR2 expression and Ca2+ release in presymptomatic AD mice." (PMID 23284867, 2012). "Recent research has proposed that leaky RyR2 channels could be valuable targets for treating cognitive decline in long‐term COVID‐19 infection." (PMID 40152069, 2025).
death (3 papers, 2015 to 2021). "Interestingly, the crossing of these PDE4D KO mice with mice harboring a mutation in the RyR2 PKA-dependent phosphorylation site (RyR2-S2808A) produces offspring that show protection against MI-induced sudden cardiac death." (PMID 33923648, 2021).
glioma (3 papers, 2021 to 2025). A benign or malignant brain and spinal cord tumor that arises from glial cells (astrocytes, oligodendrocytes, ependymal cells). "In high-grade gliomas, RYR2, MCHR2, FADS6, HTR2C, CMTM3, APH1A, and PFN1 genes are related to membrane function." (PMID 37239411, 2023).
Hyperinsulinemia (3 papers, 2013 to 2024). An increased concentration of insulin in the blood. "In agreement, our mice with mutation S2814D in RyR2 exhibited basal hyperinsulinemia in vivo and in vitro." (PMID 23516528, 2013). "To determine whether mutation S2814D in RyR2 has any effect on pancreatic structure and thereby causes basal hyperinsulinemia, we performed histological sectioning of pancreata from WT and S2814D mice." (PMID 23516528, 2013). "Therefore, the observed phenotype of basal hyperinsulinemia in S2814D mice is primarily due to the gain-of-function defect in RyR2." (PMID 23516528, 2013). "This chronic in vivo defect in RyR2 resulted in basal hyperinsulinemia." (PMID 23516528, 2013). "RyR2 was upregulated in GK compared to CON SAN, and it would be interesting to investigate if the expression of pancreatic β-cell RyR2 is also altered in GK rat which in turn might partly underlie the hyperinsulinemia previously reported in GK compared to CON rat." (PMID 30246030, 2018).
insulinoma (3 papers, 2015 to 2023). "Deletion of RyR2 from the rat insulinoma INS-1 (RyR2KO) enhanced IP3 receptor activity stimulated by 7.5 mM glucose, coincident with reduced levels of the protein IP3Receptor Binding protein released with Inositol 1,4,5 Trisphosphate (IRBIT)." (PMID 35562179, 2022). "Thimerosal, an oxidizing agent that effectively enhances the activity of skeletal RyR1 and cardiac RyR2 channels, releases Ca2+ from InsP3-insensitive ER Ca2+ pools in RINm5F insulinoma cells and from β-cells isolated from ob/ob mice." (PMID 26046640, 2015). "The ER Ca2+ channel ryanodine receptor 2 (RyR2) is required for maintenance of insulin content and glucose-stimulated insulin secretion, in part, via regulation of the protein IRBIT in the insulinoma cell line INS-1." (PMID 37141277, 2023).
ovarian carcinoma (3 papers, 2020 to 2023). A malignant neoplasm originating from the surface ovarian epithelium. "Finally, to determine if the genes that display altered mRNA expression levels in ovarian cancer patient samples (PIK3CA, TTN, RYR2, KMT2C, KRAS, PTEN, and ARID1A) have any clinical value, we checked the effect of their expression on recurrence and survival of patients with ovarian cancer." (PMID 32626534, 2020). "In addition to that, the function of TTN, CSDM3, RYR2, USH2A and SYNE1 has never been established in ovarian cancer." (PMID 32626534, 2020).
pancreatic cancer (3 papers, 2022 to 2024). "In pancreatic cancer, inhibition of RYR2 suppressed cell proliferation, migration as well as invasiveness via induction of PTEN expression." (PMID 39658878, 2024). "PTEN expression is increased by RYR2 knockdown, whereas increased RYR2 expression inhibits PTEN expression in pancreatic cancer cells." (PMID 35955916, 2022).
Sinus bradycardia (3 papers, 2022 to 2025). Bradycardia related to a mean resting sinus rate of less than 50 beats per minute. "Dysfunction of pacemaker cells has also been implicated in CPVT, such as sinus bradycardia in RyR2-R420Q patients, and progressive or complete AV block." (PMID 40612651, 2025). "Sinus bradycardia in the resting state has been reported in some RYR2 mutation carriers and in phenotypically affected CPVT patients." (PMID 36340715, 2022). "Most CPVT patients demonstrate a prominent sinus bradycardia in resting ECG, which may result from the diastolic calcium leakage from the ryanodine receptor, resulting from either RyR2 or CASQ2 mutations." (PMID 38053087, 2023). "In the present study, ECG showed sinus tachycardia in proband and his mother without phenotypic effects, rather than sinus bradycardia as reported in RYR2 mutation carriers, but it was consistent with the case reported by Jiang." (PMID 36340715, 2022).
thyroid carcinoma (3 papers, 2021 to 2022). "For example, RYR1 in cholangiocarcinoma (CHOL) and RYR3 in testicular germ cell tumors (TGCT) only had missense mutations, and RYR2 in CHOL and RYR3 in thyroid carcinoma (THCA) only had silent mutations." (PMID 36167878, 2022). "Moreover, RYR2 expression is correlated with poor prognosis in patients with thyroid carcinoma, and strong RYR2 upregulation was found in a BC cell line upon EGF-induced epithelial-to-mesenchymal transition." (PMID 34888385, 2021).
allergic asthma (2 papers, 2011 to 2022). A asthma with a basis in a pathological type I hypersensitivity reaction. "Ryanodine receptor 2 (RyR2) is a risk gene factor for childhood allergic asthma." (PMID 36186445, 2022). "RYR2, CHRM2 and TNS3 polymorphysms were confirmed as associated with allergic asthma onset risk in an independent pediatric population." (PMID 21359210, 2011).
Anxiety (2 papers, 2020 to 2026). Intense feelings of nervousness, tension, or panic often arise in response to interpersonal stresses. "Leaky RyR2 channels were also associated with increased anxiety determined using the elevated plus maze (EPM) test." (PMID 32897880, 2020). "We assessed offspring anxiety levels during the elevated plus maze (EPM) test, the expression of pro-neuroplastic proteins in the offspring brain, the excitability of brainstem monoamine and hippocampal glutamate neurons, and the expression and activity of ryanodine receptors (RyR2)." (PMID 40855004, 2026).
atherosclerosis (2 papers, 2022 to 2025). A disease characterized by the build-up of fatty material and calcium deposition in the arterial wall resulting in partial or complete occlusion of the arterial lumen. "RYR2 regulates T-cell calcium signaling, and gain-of-function mutations lead to increased IL-2 secretion in CD4+ T cells, which is a novel immune cell infiltration-related biomarker in atherosclerosis diagnosis." (PMID 40894479, 2025). "In GSE20129 dataset, CARTPT, RYR2, CNTN4, PDZRN3, and SLC22A3 all showed differential expression levels in atherosclerosis vs. nonatherosclerotic samples." (PMID 35915606, 2022).
autism (2 papers, 2015 to 2016). Persistent deficits in social interaction and communication and interaction as well as a markedly restricted repertoire of activity and interest as well as repetitive patterns of behavior. "For example, modeling sex/gender-differential effects in a genome-wide association study (GWAS) reveals autism risk loci at RyR2 and UPP2 in multiplex families." (PMID 25524786, 2015).
bipolar disorder (2 papers, 2015 to 2020). A disorder of the brain that causes unusual shifts in mood, energy, activity levels and the ability to carry out day-to-day tasks. "The result showed that 6 genes (including MAD1L1, JAM3, MYL12B, MYL12A, ITIH1 and RYR2) had been reported to be significant associated with bipolar disorder in at least one genetic study." (PMID 26193471, 2015).
brain ischemia (2 papers, 2017 to 2019). Diminished or absent blood supply to the brain caused by obstruction (thrombosis or embolism) of an artery resulting in neurologic damage. "RyR2 also has an impact on Ca2+ homeostasis in the brain during cerebral ischemia." (PMID 30678657, 2019). "Interestingly, post-translational modifications of RyR2 were reported in cerebral ischemia, where endogenous RyRs undergo S-nitrosylation and S-gluthathionylation processes that resulted in high activity channels and ultimately lead to cortical neuronal death." (PMID 28476886, 2017).
coronary artery disease (2 papers, 2015 to 2026). "Ryanodine receptor 2 (RyR2) hyperactivity is frequently observed in structural heart disease (SHD), commonly caused by ischemic heart disease." (PMID 41609498, 2026).
COVID-19 (2 papers, 2022 to 2023). A disease caused by infection with severe acute respiratory syndrome coronavirus 2. "Indirect evidence has demonstrated the association between COVID-19 and RYR2 expression." (PMID 37109540, 2023). "COVID-19 may cause hypoxia in patients, and RYR2 expression can be significantly reduced upon hypoxic exposure." (PMID 37109540, 2023).
fibrosis (2 papers, 2020 to 2024). the formation of excess fibrous connective tissue in an organ or tissue in a reparative or reactive process. "In addition, aldosterone infusion markedly increased myocardial fibrosis and inflammation, decreased SERCA2a protein expression and the phosphorylation of PLB at Thr17, and increased NCX1 protein expression and the phosphorylation of RyR2 in MD1‐KO mice." (PMID 31994333, 2020).
hypertensive heart disease (2 papers, 2020 to 2023). Abnormal enlargement of the heart resulting from long-standing hypertension. "In hypertensive heart disease, an increase in NCX expression/activity and an increase in RyR2 phosphorylation at S2808 occurs late during the disease course." (PMID 37372947, 2023).
idiopathic dilated cardiomyopathy (2 papers, 2021 to 2024). Decreased function of the heart associated with cardiac enlargement and congestive heart failure, of unknown cause. "We examined whether RyR2 clusters smaller than 10 localizations might be nondyadic as has been described in human idiopathic dilated cardiomyopathy myocytes." (PMID 39365674, 2024).